KRT19 (keratin 19)
Diseases named in the same sentence as KRT19 in open-access papers (continued):
Sharing a sentence is not in itself a finding about the gene and the disease.
neuroendocrine carcinoma (8 papers, 2011 to 2025). A malignant neuroendocrine neoplasm composed of cells containing secretory granules that stain positive for NSE and chromogranin. "The majority of the tumor was a high-grade neuroendocrine carcinoma with features of a small cell carcinoma that was positive for chromogranin, synaptophysin, and cytokeratin 19 and negative for hepatocellular antigen and alpha-fetoprotein (AFP)." (PMID 29147223, 2011).
diabetes (7 papers, 2012 to 2025). "For example, cytokeratin-19-fragment CYFRA21-1 was detected in 10 unhealthy statuses, including hypertension + diabetes (P = 3.71 × 10−97) and diabetes (P = 4.52 × 10−70)." (PMID 36379988, 2022). "Interestingly, the one notable exception was Keratin 19 (KRT19), a ductal epithelial marker, which showed reduced expression in PDAC-associated diabetes relative to the non-diabetic PDAC cohort." (PMID 40244011, 2025).
neuroblastoma (7 papers, 2011 to 2025). Neuroblastoma (NB) is the most common solid, extracranial childhood tumor. "In our study, a low methylation frequency of SCNN1A, PRKCDBP and KRT19 is significantly associated with favorable outcome in neuroblastoma." (PMID 21314941, 2011). "KRT19 extinction is due to the methylation of its promoter, as described in uterine leiomyoma, renal cell carcinoma, as well as in neuroblastoma, another neural crest cell derived tumor." (PMID 26460615, 2015). "We present eight genes (KRT19, PRKCDBP, SCNN1A, POU2F2, TGFBI, COL1A2, DHRS3 and DUSP23) that are methylated in neuroblastoma, most of them not previously reported as such, some of which also distinguish between biological subsets of neuroblastoma tumors." (PMID 21314941, 2011).
bladder cancer (6 papers, 2017 to 2025). "Keratin 19 normally exists in serum in the form of an oligomer in very low amounts; in bladder cancer, CK19 amounts increase, cancer cells undergo necrosis and exfoliation, and CK19 is released in the form of dissolved fragments." (PMID 40748011, 2025). "Neither this study nor another found a change in cytokeratin-19 or -20 expression, which have also been associated with bladder cancer, in Sh-associated versus non-associated bladder cancers." (PMID 39250522, 2024). "In this study, we evaluate the diagnostic values of Cytokeratin 19 fragment (CYFRA21‐1), Fibrin/fibrinogen degradation products (FDP) and CYFRA21‐1 + FDP in bladder cancer, with the objective to expand the application scope of urinary tumor markers in the diagnosis of bladder cancer." (PMID 40748011, 2025).
ductal adenocarcinoma (6 papers, 2015 to 2021). "We next examined the frequency of KRT14 expression in KRT19+ cells in premalignant and malignant breast lesions, such as ductal carcinoma in situ (DCIS; n = 5) and invasive ductal carcinomas (IDC; n = 6)." (PMID 35187501, 2021). "Instead, cytokeratin 19 (CK19), cytokeratin 7 (CK7), and MUC 1 were slightly positive especially in the solid area, which indicated differentiation of ductal adenocarcinoma." (PMID 28114893, 2017).
esophageal squamous cell carcinoma (6 papers, 2008 to 2024). Esophageal squamous cell carcinoma (ESCC) is a type of esophageal carcinoma (EC) that can affect any part of the esophagus, but is usually located in the upper or middle third. "The purpose of this study is to evaluate the predictive significance of preoperative serum level of cytokeratin 19 fragments (Cyfra21-1) and squamous cell carcinoma antigen (SCC-Ag) after complete resection in patients with stage II esophageal squamous cell carcinoma (ESCC)." (PMID 22999061, 2012).
head and neck squamous cell carcinoma (6 papers, 2006 to 2024). A squamous cell carcinoma that arises from any of the following anatomic sites: lip and oral cavity, nasal cavity, paranasal sinuses, pharynx, larynx, and salivary glands. "CYFRA 21-1 (cytokeratin 19 fragment) and C-reactive proteins (CRP) were separately reported to be associated with prognosis of head and neck squamous cell carcinoma." (PMID 26292957, 2015).
Pleural effusion (6 papers, 2013 to 2024). The presence of an excessive amount of fluid in the pleural cavity. "Pleural effusion and pulmonary metastasis increased, however then shrank and serum cytokeratin 19 fragment levels decreased." (PMID 29988633, 2018). "We investigated whether tumour markers carcinoembryonic antigen (CEA), neuron-specific enolase (NSE), cancer antigen 125 (CA-125), and cytokeratin 19 fragment (CYFRA 21-1) in pleural effusions and serum can be used to distinguish pleural effusion aetiology." (PMID 29472801, 2018).
thymoma (6 papers, 2014 to 2022). A neoplasm arising from the epithelial cells of the thymus. "CK19 (KRT19) and TdT were included in the IHC analysis to index the location for tumor epithelial cells and immature T lymphocytes in type B thymoma, respectively." (PMID 31967407, 2020). "The tumor expressed the typical keratin 19 positivity of thymoma; no CD5 or CD117 positive EC were found." (PMID 25105128, 2014).
triple-negative breast carcinoma (6 papers, 2014 to 2025). An invasive breast carcinoma which is negative for expression of estrogen receptor (ER), progesterone receptor (PR), and human epidermal growth factor receptor 2 (HER2). "We used MDA-MB-231 triple-negative breast cancer (TNBC) cells with CRISPR-Cas9 mediated KRT19 knockout (KO) and confirmed complete ablation of K19 expression by Western blotting and RNA-sequencing (RNA-seq)." (PMID 37592256, 2023).
adenoma (5 papers, 2010 to 2023). A neoplasm arising from the epithelium. "One such example is CYFRA 21-1 (cytokeratin 19 fragment), which showed an AUC of 0.73 for detecting advanced adenomas in a general cancer screening setting." (PMID 34503217, 2021).
benign thyroid tumors (5 papers, 2015 to 2025). "These include Hector Battifora mesothelial epitope-1 (HBME-1), cytokeratin 19 (CK19), and Galectin-3, which are the most widely recognized markers that are expressed in over 95% of PTC, with very low expression in benign thyroid neoplasms." (PMID 40940966, 2025).
head and neck cancer (5 papers, 2008 to 2020). A primary or metastatic malignant neoplasm affecting the head and neck. "Previously, keratin 19 was reported to be downregulated in head and neck cancers." (PMID 18195710, 2008).
oral cancer (5 papers, 2014 to 2021). "Of these, only carcinoembryonic antigens (CEA) and soluble fragment of cytokeratin 19 (CYFRA21) were found to be significantly associated with oral cancer." (PMID 34711249, 2021).
renal cell carcinoma (5 papers, 2007 to 2023). "KRT19 (CK19) encodes an element of the cytoskeleton and shows frequent DNA methylation in renal cell carcinoma (RCC) cell lines and primary RCC, without methylation in normal renal tissue." (PMID 21314941, 2011).
sarcoma (5 papers, 2016 to 2024). A usually aggressive malignant neoplasm of the soft tissue or bone. "To exclude the possibility that sarcomatoid tumours are in fact sarcomas arising from CRISPR/Cas9 targeted fibroblasts, we performed IHC staining of the epithelial marker cytokeratin 19 (CK19) and E-cadherin." (PMID 26916719, 2016).
basal cell carcinoma (4 papers, 2020 to 2024). A carcinoma involving the basal cells. "Nevertheless, they can be distinguished relying on some microscopic and immunohistochemical findings: for example, the PA is positive for cytokeratin 19 and negative for Bcr-Ep4, while the opposite is seen in the intraoral basal cell carcinoma." (PMID 39597858, 2024).
chronic periodontitis (4 papers, 2018 to 2024). A chronic inflammatory process that affects the tissues that surround and support the teeth. "In periodontitis, we consistently found concentrated CD45+ adaptive immune cells near SK cells; we also found isolated expression of KRT19-high cells in the keratinized mucosa (AG) uniquely attracting CD45+ immune cells (inset)." (PMID 38876998, 2024).
dysplasia (4 papers, 2009 to 2025). A usually neoplastic transformation of the cell, associated with altered architectural tissue patterns. "KRT19 has been associated with the progression of dysplasia in leukoplakia." (PMID 40650045, 2025). "Also, the keratin 19 extension into suprabasal cells has been associated with the evolving features of dysplasia." (PMID 38891785, 2024).
Hashimoto thyroiditis (4 papers, 2018 to 2024). An autoimmune disorder caused by the production of autoantibodies against thyroid tissue. "However, the expression of cytokeratin-19, galectin-3, HBME1, and loss of expression of CD56 are also detected in 20%, 20–40%, 20%, and 7–90% of patients with Hashimoto’s thyroiditis, respectively." (PMID 30428594, 2018). "Immunomarkers such as Hector Battifora mesothelial-1 and cytokeratin 19 can aid in differentiation, as they are expressed in PTC but not in Hashimoto’s thyroiditis, facilitating accurate diagnosis." (PMID 38773600, 2024).
leiomyoma (4 papers, 2012 to 2021). A well-circumscribed benign smooth muscle neoplasm characterized by the presence of spindle cells with cigar-shaped nuclei, interlacing fascicles, and a whorled pattern. "Increased levels of α-SMA and decreased levels of vimentin and KRT-19 identified the leiomyoma tumor cells." (PMID 33777725, 2021). "KRT19, which has also been reported previously to be silenced by promoter hypermethylation in fibroids, was the most downregulated gene in all fibroids compared with normal myometria using this analysis." (PMID 31851934, 2019). "To understand the in vivo relevance of how DNA methylation affects gene function, we analyzed protein levels of KLF11, DLEC1 and KRT19 in human leiomyoma and matched normal myometrial tissues using western blot." (PMID 22428009, 2012). "KRT19 protein levels in 8 subjects were lower (25%) in leiomyoma than myometrial tissues, and only 1 subject had higher KRT19 protein levels in leiomyoma compared with myometrial tissues." (PMID 22428009, 2012). "The detailed CpG methylation level of primary leiomyoma (n = 7) and matched myometrial (n = 7) tissues verified the hypermethylated state of the KRT19 promoter in uterine leiomyoma compared with adjacent normal myometrium." (PMID 22428009, 2012). "Finally, we studied the KRT19 promoter via sequencing of bisulfite-treated genomic DNA from uterine leiomyoma and myometrial tissues from 7 subjects." (PMID 22428009, 2012). "5-aza-dC treatment of primary cultured leiomyoma smooth muscle cells led to an increase in KLF11 mRNA by 1.4-fold, DLEC1 mRNA by 2-fold, and KRT19 mRNA by 2.4-fold suggesting that these three genes are epigenetically regulated in leiomyomas." (PMID 22428009, 2012). "Incubation of primary leiomyoma smooth muscle cells with a DNA methyltransferase inhibitor restored KLF11, DLEC1 and KRT19 mRNA levels." (PMID 22428009, 2012).
lymphoma (4 papers, 2013 to 2025). A malignant (clonal) proliferation of B- lymphocytes or T- lymphocytes which involves the lymph nodes, bone marrow and/or extranodal sites. "A broad panel of immunohistochemistry excluded lymphoma and nephroblastoma, confirming extra-adrenal paraganglioma based on strong positivity for anti-synaptophysin, neuron-specific enolase, chromogranin A, and cytokeratin 19 antibodies." (PMID 40948633, 2025).
mesothelioma (4 papers, 2012 to 2021). A usually malignant and aggressive neoplasm of the mesothelium which is often associated with exposure to asbestos. "These immunostains include HBME-1(named after the laboratory of Dr. Hector Battifora and MEsothelioma), Galectin-3, cytokeratin 19 (CK19), and CD56." (PMID 34711014, 2021). "The cytokeratin-19/CEA ratio is a useful marker for mesothelioma diagnosis due to the high level of cytokeratin (18 and 19) expression in mesothelial cells." (PMID 30301262, 2018). "High molecular weight cytokeratins (18&19) are expressed in mesothelial cells and soluble cytokeratin-19 was previously found in high concentration in two familial cases of mesothelioma." (PMID 23516439, 2013). "Additionally, cytokeratin-19 was previously found in two hereditary cases of mesothelioma." (PMID 30301262, 2018).
skin cancer (4 papers, 2020 to 2023). "For example, previous studies have reported that KRT8, KRT18, and KRT19 are expressed in most cancers, including skin cancer, whereas our analysis revealed that their expression is low in skin cancer samples." (PMID 35267493, 2022).
ameloblastoma (3 papers, 2024). The most common odontogenic tumor, arising from the epithelial component of the embryonic tooth and usually affecting the molar-ramus region of the mandible or maxilla. "Peripheral ameloblastoma is positive for cytokeratin 19, which can be differentiated from BCC." (PMID 39703280, 2024).
Barrett esophagus (3 papers, 2015 to 2021). Esophageal lesion lined with columnar metaplastic epithelium which is flat or villiform. "Moreover, consistent with the published report, we can demonstrate increased mRNA expression of the Barrett's esophagus associated genes Cckbr, Tff2, and Krt19 (data not shown)." (PMID 26460825, 2015). "Transcriptomics showed that the combination of SLC26A9 and the other four genes, SINHCAF, MICB, KRT19, and MT1X, became a gene signature that predicts the overall survival of esophageal adenocarcinoma." (PMID 35008199, 2021).
biliary tract cancer (3 papers, 2016 to 2023). "Similarly, knockdown of ELF3 in biliary tract cancer cells resulted in upregulation of mesenchymal markers such as ZEB1/2, VIM and TWIST1 accompanied by the downregulation of KRT19." (PMID 36864480, 2023).
chronic pancreatitis (3 papers, 2012 to 2023). A chronic inflammatory process causing damage and fibrosis of the pancreatic parenchyma. "Chronic pancreatitis induced a stroma-rich and duct-like structure and increased the formation of ADM and mPanIN lesions, in line with an increased cytokeratin 19 (CK19)-stained area." (PMID 28738823, 2017).
fibrosis (3 papers, 2020 to 2024). the formation of excess fibrous connective tissue in an organ or tissue in a reparative or reactive process. "As expected, percentage of collagen+ or smooth muscle alpha-actin (α-SMA) + or KRT19+ areas with S3-S4 fibrosis in patients was markedly higher than those of S1-S2 patients (p < 0.05, p < 0.01)." (PMID 38646644, 2024). "The results showed that percentage of collagen+ or KRT19+ areas with S2, S3, and S4 fibrosis in patients was markedly higher than that of S1 patients (p < 0.01)." (PMID 38646644, 2024). "Additionally, the percentage of collagen+ or KRT19+ area of S4 fibrosis was significantly higher than that of S2 and S3 fibrosis (p < 0.05)." (PMID 38646644, 2024).
Hepatitis (3 papers, 2012 to 2023). Inflammation of the liver. "Notably, ACHRG IgM was associated with pneumonitis, anti-cytokeratin 19 IgM with dermatitis, and anti-thyroglobulin IgG with hepatitis." (PMID 38152395, 2023). "Notably, IgM antibodies against ACHRG in pneumonitis, cytokeratin 19 during dermatitis, and IgG antibody against thyroglobulin during hepatitis were significantly elevated during toxicity events compared with 12-week control samples." (PMID 38152395, 2023).
Hyperglycemia (3 papers, 2024 to 2025). An increased concentration of glucose in the blood. "Additionally, we observed interactions involving KRT19, SNAI1, and OCLN that suggest a potential association of hyperglycemia with fibrosis-related pathways in TM." (PMID 39764143, 2024).
ovarian tumors (3 papers, 2009 to 2024). "E-cadherin, N-cadherin, cytokeratin 19 and vimentin mRNA expression levels in human ovarian tumor-primary cultures." (PMID 28934230, 2017).
pneumonia (3 papers, 2008 to 2022). An acute, acute and chronic, or chronic inflammation focally or diffusely affecting the lung parenchyma, caused by an infection in one or both of the lungs (by bacteria, viruses, fungi, or mycoplasma.). "Results suggested that 5 proteins with greater node degrees [i.e. catenin beta-1 (CTNNB1), integrin beta-1 (ITGB1), catenin alpha-1 (CTNNA1), dynamin-2 (DNM2), Keratin, type I cytoskeletal 19 (KRT19)] might function as crucial players in pneumonia-related bacterial infection in FMD." (PMID 36387401, 2022).
small cell lung carcinoma (3 papers, 2010 to 2025). Small cell lung cancer (SCLC) is a highly aggressive malignant neoplasm, accounting for 10-15% of lung cancer cases, characterized byrapid growth, and early metastasis. "Small cell lung carcinoma was suspected, upon admission, but high serum levels of squamous cell carcinoma antigen and cytokeratin-19 fragments were present." (PMID 29548309, 2018). "In small cell lung cancer (SCLC) patients, serum pro-gastrin-releasing peptide (ProGRP), neuron-specific enolase (NSE), and cytokeratin 19 fragment (CYFRA 21-1) levels closely correlated with treatment response and overall survival." (PMID 41294748, 2025).
synovial sarcoma (3 papers, 2013 to 2025). "The results indicate high expression levels of E-cadherin and cytokeratin 19 in epithelial cells and stronger reactions for vimentin and S100b in spindle cells of biphasic synovial sarcomas." (PMID 41155410, 2025).
alcoholic hepatitis (2 papers, 2021 to 2025). Acute hepatitis resulting from ingestion of alcohol. "Mallory-Denk bodies, the hallmark of alcoholic hepatitis and steatohepatitis, contain cytokeratin-18 (CK-18) and cytokeratin-19 (CK-19), while the serum CK-18 and CK-19 levels were increased in AH patients in previous studies." (PMID 34068269, 2021).
benign prostate hyperplasia (2 papers, 2017 to 2024). "Additionally, the biomarkers FLNA, KRT19 and age were able to improve the classification of whether patients had benign prostate hyperplasia or cancer over the PSA test alone." (PMID 29682400, 2017).
bile duct carcinoma (2 papers, 2022 to 2024). "KRT19 plays an important role in the pathogenesis of CCA and is a biomarker for the diagnosis of bile duct carcinoma." (PMID 36300097, 2022).
biliary atresia (2 papers, 2012 to 2022). A rare, biliary tract disease characterized by progressive obliterative cholangiopathy of the intra- and extrahepatic bile ducts, occurring in the embryonic/ perinatal period, leading to severe and persistent neonatal jaundice and acholic stool. "induction and duration of illness after rhesus rotavirus exposure effect on the expression of cytokeratin-7 and cytokeratin-19 mice models of biliary atresia." (PMID 36451979, 2022).
cholesteatoma (2 papers, 2012 to 2018). A pathologic process characterized by the proliferation of keratinizing squamous epithelium resulting in the accumulation of keratin and cells in the middle ear and/or mastoid. "KRT19 expression might have prognostic significance, its lower level in pediatric cases could be associated with the more aggressive behavior of childhood cholesteatoma." (PMID 30021014, 2018). "The analysis of the cytokeratin-expression revealed an up-regulation of Keratin 6 A and B, Keratin 18, Keratin 19 and Keratin 81 in cholesteatoma compared to normal skin." (PMID 23285167, 2012). "Based on our results it can be concluded that the expression pattern of KRT1, KRT10 and KRT19 genes seen in our pediatric cholesteatoma samples suggests elevated immature keratinocyte differentiation and elevated proliferation potential, especially in recurrent samples." (PMID 30021014, 2018). "In addition to already described up-regulated mRNAs in cholesteatoma, such as MMP9, DEFB2 and KRT19, we identified 3558 new cholesteatoma-related transcripts." (PMID 23285167, 2012). "KRT19 with a tumor suppressor potential might restrict the recurrence of cholesteatoma." (PMID 30021014, 2018).
clear cell renal cell carcinoma (2 papers, 2021 to 2022). "Interestingly, in clear cell renal cell carcinomas, the detection of KRT19 along with KRT7 was associated with better clinical outome." (PMID 36033462, 2022). "However, high KRT7 expression was associated with better OS in papillary renal cell carcinoma and the KRT7/KRT19 expressing subtype was associated with better outcomes in clear cell renal cell carcinoma." (PMID 34070214, 2021).